SART3 (spliceosome associated factor 3, U4/U6 recycling protein)
Description:
U6 snRNP-binding protein that functions as a recycling factor of the splicing machinery. Promotes the initial reassembly of U4 and U6 snRNPs following their ejection from the spliceosome during its maturation. Also binds U6atac snRNPs and may function as a recycling factor for U4atac/U6atac spliceosomal snRNP, an initial step in the assembly of U12-type spliceosomal complex. The U12-type spliceosomal complex plays a role in the splicing of introns with non-canonical splice sites. May also function as a substrate-targeting factor for deubiquitinases like USP4 and USP15. Recruits USP4 to ubiquitinated PRPF3 within the U4/U5/U6 tri-snRNP complex, promoting PRPF3 deubiquitination and thereby regulating the spliceosome U4/U5/U6 tri-snRNP spliceosomal complex disassembly. May also recruit the deubiquitinase USP15 to histone H2B and mediate histone deubiquitination, thereby regulating gene expression and/or DNA repair. May play a role in hematopoiesis probably through transcription regulation of specific genes including MYC (By similarity). Regulates Tat transactivation activity through direct interaction. May be a cellular factor for HIV-1 gene expression and viral replication.
Synonyms: Tip110; KIAA0156; RP11-13G14; p110; DSAP1; P100; p110(nrb)
Tractability: PROTAC: ubiquitination databases record sites on it; its protein half-life has been measured.
Gene: Protein-coding gene on chromosome 12 (108,522,214 to 108,561,400, reverse strand). Ensembl gene ENSG00000075856.
Subcellular location: Nucleus, nucleoplasm; Nucleus, Cajal body; Nucleus speckle; Cytoplasm
Subcellular location (Human Protein Atlas): Nucleoplasm
Gene Ontology:
Molecular function: histone binding; protein binding; protein-macromolecule adaptor activity; RNA binding; U4 snRNA binding; U6 snRNA binding; U6atac snRNA binding; ubiquitin-specific protease binding; nucleic acid binding
Biological process: mRNA splicing, via spliceosome; nucleosome assembly; regulation of gene expression; regulation of RNA metabolic process; spliceosomal snRNP assembly; spliceosomal tri-snRNP complex assembly; transcription elongation-coupled chromatin remodeling; RNA processing
Cellular component: Cajal body; cytoplasm; nuclear speck; nucleoplasm; nucleus; U4/U6 snRNP; U4/U6 x U5 tri-snRNP complex; U4atac/U6atac snRNP; U6atac snRNP; ASAP complex; spliceosomal complex
Genetic constraint (gnomAD): Loss-of-function variants: 39 observed, 121.68 expected, observed/expected ratio (o/e) 0.32, 90% interval 0.25 to 0.42. The upper end of that interval is the gene's LOEUF score, 0.42, which puts it in group 1 of 6, group 1 being the genes least tolerant of losing a copy. Missense variants: 1,077 observed, 1,262.1 expected, observed/expected ratio (o/e) 0.85, 90% interval 0.81 to 0.9. Synonymous variants: 438 observed, 470.92 expected, observed/expected ratio (o/e) 0.93, 90% interval 0.86 to 1.01.
Homologues: Orthologues: chimpanzee SART3 (99% identical), macaque SART3 (99% identical), dog SART3 (92% identical), pig SART3 (91% identical), rabbit SART3 (90% identical), guinea pig SART3 (89% identical), mouse Sart3 (87% identical), rat Sart3 (86% identical), tropical clawed frog sart3 (66% identical), zebrafish sart3 (59% identical), Caenorhabditis elegans sart-3 (24% identical), Drosophila melanogaster Rnp4F (20% identical).